GPX1 (glutathione peroxidase 1)
Description:
Catalyzes the reduction of hydroperoxides in a glutathione-dependent manner thus regulating cellular redox homeostasis. Can reduce small soluble hydroperoxides such as H2O2, cumene hydroperoxide and tert-butyl hydroperoxide, as well as several fatty acid-derived hydroperoxides. In platelets catalyzes the reduction of 12-hydroperoxyeicosatetraenoic acid, the primary product of the arachidonate 12-lipoxygenase pathway.
Synonyms: GPXD; GSHPX1
Tractability: Small molecule: a structure with a bound ligand is known. PROTAC: ubiquitination databases record sites on it; its protein half-life has been measured.
Target class: Enzyme; Oxidoreductase
Gene: Protein-coding gene on chromosome 3 (49,357,174 to 49,358,605, reverse strand). Ensembl gene ENSG00000233276.
Subcellular location: Cytoplasm; Mitochondrion
Subcellular location (Human Protein Atlas): Cytosol; Predicted to be secreted
Pathways (Reactome):
Metabolism: Synthesis of 12-eicosatetraenoic acid derivatives; Synthesis of 15-eicosatetraenoic acid derivatives; Synthesis of 5-eicosatetraenoic acids
Cellular responses to stimuli: Detoxification of Reactive Oxygen Species
Gene Ontology:
Molecular function: glutathione peroxidase activity; phospholipid-hydroperoxide glutathione peroxidase activity; protein binding; protein tyrosine kinase binding; SH3 domain binding; peroxidase activity
Biological process: arachidonate metabolic process; cell redox homeostasis; cellular response to oxidative stress; epigenetic regulation of gene expression; glutathione metabolic process; heart contraction; hydrogen peroxide catabolic process; lipoxygenase pathway; negative regulation of extrinsic apoptotic signaling pathway via death domain receptors; negative regulation of release of cytochrome c from mitochondria; regulation of mammary gland epithelial cell proliferation; regulation of proteasomal protein catabolic process; response to hydrogen peroxide; response to selenium ion; UV protection; positive regulation of supramolecular fiber organization; cellular oxidant detoxification; cellular response to glucose stimulus; response to estradiol; response to folic acid; response to glucose; response to hormone; response to nicotine; response to oxidative stress; response to vitamin E
Cellular component: cytoplasm; cytosol; Lewy body; mitochondrion; mitochondrial matrix
Genetic constraint (gnomAD): Loss-of-function variants: 9 observed, 11.36 expected, observed/expected ratio (o/e) 0.79, 90% interval 0.48 to 1.38. The upper end of that interval is the gene's LOEUF score, 1.38, which puts it in group 5 of 6, group 1 being the genes least tolerant of losing a copy. Missense variants: 266 observed, 271.95 expected, observed/expected ratio (o/e) 0.98, 90% interval 0.88 to 1.08. Synonymous variants: 142 observed, 126.24 expected, observed/expected ratio (o/e) 1.12, 90% interval 0.98 to 1.29.
Homologues: Orthologues: chimpanzee GPX1 (98% identical), macaque GPX1 (96% identical), dog GPX1 (94% identical), pig GPX1 (92% identical), rabbit GPX1 (90% identical), rat Gpx1 (86% identical), mouse Gpx1 (85% identical), tropical clawed frog gpx1 (46% identical), Caenorhabditis elegans gpx-3 (34% identical), Caenorhabditis elegans gpx-5 (33% identical), zebrafish gpx9 (32% identical), Caenorhabditis elegans gpx-2 (30% identical), and 2 more. Paralogues in human: GPX2 (63% identical), GPX5 (46% identical), GPX3 (42% identical), GPX6 (39% identical), GPX4 (31% identical), GPX7 (31% identical), GPX8 (28% identical).
Diseases named in the same sentence as GPX1 in open-access papers:
GPX1 is named in the same sentence as 295 diseases in open-access papers, as found by Europe PMC text mining. Sharing a sentence is not in itself a finding about the gene and the disease. The quoted sentences say what the papers report.
Insulin resistance (60 papers, 2007 to 2025). Increased resistance towards insulin, that is, diminished effectiveness of insulin in reducing blood glucose levels. "Confirmation in humans was derived from the insulin resistance already observed in pregnant women in association with increased erythrocyte GPx1 activity and also from enhanced insulin sensitivity in patients with global genetic selenoproteins deficiency." (PMID 35204134, 2022). "There are some selenoproteins with potentially harmful effects, such as GPX1, which is associated with insulin resistance and type 2 diabetes." (PMID 36364721, 2022). "The transgenic mice with GPx1 deficiency or overexpression showed additional regulatory functions of GPx1 in reactive oxygen and nitrogen species and insulin secretion and insulin resistance." (PMID 35624786, 2022). "A previous study reported that GPx1 overexpression can cause insulin resistance, decrease insulin-mediated signal transduction, and cause obesity." (PMID 34579115, 2021). "For example, expression of a couple of selenoproteins, including Gpx1, selenoprotein P and selenoprotein M, is associated with insulin resistance and/or obesity." (PMID 27653523, 2017). "A similar phenomenon is observed in skeletal muscle, where overexpression of the antioxidant enzyme glutathione peroxidase-1 (GPx1) in mice was shown to cause insulin resistance." (PMID 25278906, 2014). "Regarding genetic variations, SNPs associated with obesity and insulin resistance have been described for the GPX1 and GPX7 genes." (PMID 24562334, 2014). "Mice overexpressing glutathione peroxidase, Gpx1, developed insulin resistance associated with hyperinsulinemia, hyperglycemia, obesity and a 70% reduction in insulin-stimulated phosphorylation of insulin receptors, compared to wild type control mice." (PMID 23730255, 2012). "Prolonged GPx-1 activation in animal models may disrupt insulin signaling pathways, and GPx-1 overexpression has been associated with obesity and insulin resistance in experimental settings, whereas its reduction tends to mitigate these effects." (PMID 39469571, 2024). "Meanwhile, increased insulin-stimulated SOD1 expression suggests increased O2• − dismutation capacity, which may integrate with the PRX2 and GPx1 responses and counteract the chronic oxidative stress associated with insulin resistance." (PMID 37812879, 2023). "Overexpression of the AOX enzyme Gpx1 led to insulin resistance and hyperglycemia in mice, whereas a deficiency of Gpx1 may actually protect mice from obesity-induced insulin resistance." (PMID 37237860, 2023). "In our study population, few participants would have had maximized activities or concentrations of selenoproteins; animal studies have shown that not only excessive levels of GPx1 but also low levels of GPx1 and other “stress-related” selenoproteins can cause insulin resistance and hyperglycaemia." (PMID 23028897, 2012). "However, it is worth noting that taking GPX1 as an example, while it has anti-inflammatory and antioxidant effects, it has also been found to be associated with insulin resistance and type 2 diabetes, which fully illustrates the complexity of selenoproteins’ biological functions." (PMID 39329105, 2024). "In addition, GPX1 is ubiquitously expressed in all tissues and the overexpression of GPX1 could cause insulin resistance and obesity." (PMID 27286733, 2016). "In metabolic diseases such as insulin resistance and obesity, the expression level of GPX1 has a significant impact on insulin signaling pathways." (PMID 40599237, 2025). "Preclinical studies corroborate this: selenium supplementation restores GPX1 activity in obese rodents, ameliorating insulin resistance and hepatic steatosis." (PMID 40416378, 2025). "A correlation was observed between increased erythrocyte glutathione peroxidase 1 (GPx1) activity and insulin resistance in pregnant women." (PMID 38877419, 2024).
Insulin resistance (continued). "Transgenic animal models have found increased GPx1 expression interferes with insulin signaling by removing hydrogen peroxide, leading to the development of insulin resistance, hyperglycemia, and obesity." (PMID 37275636, 2023). "Conversely, overexpression of GPx1 protects mice from acute oxidative stress, but these mice later develop hyperglycemia, hyperinsulinemia, increased β-cell mass, insulin resistance, and obesity." (PMID 37373256, 2023). "As well, another important conclusion is that if the activity ratio GPx1/Nox4 is too high, the Nrf2-dependent stimulation of antioxidant protections is compromised, and insulin resistance develops." (PMID 37373256, 2023). "Adipose tissue exhibits unique carbonylated proteins in obesity and insulin resistance, including GPx1." (PMID 35624726, 2022). "This was preliminarily confirmed by experiments on transgenic mice: those over-expressing GPx1 showed insulin resistance and hyperinsulinemia, while knockout models exhibited improved insulin sensitivity." (PMID 35204134, 2022). "In this regard, GPx1-knockout-mice were protected from insulin resistance induced by a high-fat diet due to increased H2O2 production and inactivation of PTEN." (PMID 36438755, 2022). "Permanently high activity of the H2O2-detoxifying enzyme glutathione peroxidase 1 (GPX1) has been positively correlated with the early development of insulin resistance and T2D in animal models." (PMID 33893069, 2021). "Studies have shown that Gpx1 overexpression leads to enhanced protection against oxidative stress, but Gpx1-overexpressing mice exhibit obesity, insulin resistance, hyperinsulinemia, and hyperglycemia." (PMID 34679770, 2021). "Selenoneine feeding decreased hepatic Gpx1 and Selenop mRNA levels, whereas excessive selenium consumption promoted the production of Gpx1 and Selenop, resulting in enhanced insulin resistance." (PMID 32604760, 2020). "Selenoneine significantly decreased hepatic Gpx1 and Selenop mRNA levels in Fxr-null mice, which exhibit higher serum glucose and insulin resistance." (PMID 32604760, 2020). "The over-expression of GPx1 in transgenic mice was found to lead to the development of insulin resistance, hyperglycemia, hyperinsulinemia, and obesity." (PMID 27142520, 2016). "The same correlation was also observed between increased erythrocyte GPx1 activity and mild insulin resistance in pregnant women." (PMID 27142520, 2016). "Another study suggested that both high and low expression levels of GPx1 and other related selenoproteins are harmful because of their effects on insulin resistance and hyperglycemia." (PMID 27142520, 2016). "Mice overexpressing GPX-1, the most abundant selenoprotein in mammals, develop hyperglycemia, hyperinsulinemia and insulin resistance by 24 weeks of age." (PMID 23603996, 2013). "A recent study has shown that mice lacking one of the key enzymes involved in the elimination of physiological ROS, glutathione peroxidase 1 (Gpx1), were protected from high-fat-diet-induced insulin resistance." (PMID 20808936, 2010). "Mice with elevated GPx-1 expression exhibit a T2D-like phenotype characterized by obesity, hyperglycemia, hyperlipidemia, hyperinsulinemia, insulin resistance, increased pancreatic β-cell mass, glucose-stimulated insulin secretion, elevated plasma leptin levels, and hepatic lipogenesis." (PMID 39469571, 2024). "A prior study on Gpx KO mice revealed that Gpx1 deficiency enhances insulin signaling in vivo by the inhibition of PTEN, a negative modulator of the PI3K/Akt pathway, to attenuate the development of insulin resistance." (PMID 39383215, 2024). "Indeed, high levels of GPx1 protect β-cells from H2O2, thus inhibiting insulin resistance in mice and human, but a deficiency of GPx1 raises insulin sensitivity in mice and human." (PMID 38202704, 2023).
Insulin resistance (continued). "Specifically, evidence from animal studies has shown that excess production of glutathione peroxidase 1, which is the most common type of selenoprotein, may disrupt the insulin signalling pathway and lead to insulin resistance." (PMID 37299509, 2023). "In those tissues an uncontrolled reduction of intracellular ROS by a higher-than-physiological GPx1 expression might desensitize insulin signalling; this desensitization leads to insulin resistance in the context of T2D." (PMID 35204134, 2022). "Conversely, mice over-expressing GPx1 exhibited insulin resistance and hyperinsulinemia." (PMID 36438755, 2022). "However, global overexpression of GPx1 induced obesity, hyperglycemia, insulin resistance in mice, and developed type 2 diabetes-like phenotypes, which infered adverse effects of excessive selenoprotein biosynthesis and the complexity of redox status." (PMID 36438755, 2022). "Similarly, overexpression of antioxidant enzymes, such as GPx1, have been shown to reduce cellular ROS to decrease growth factor mediated signaling and promote insulin resistance." (PMID 34579115, 2021). "Moreover, it is reported that Gpx1 is related to diabetes, and Gpx1 overexpressed mice exhibited insulin resistance, hyperinsulinemia, obesity and hyperglycemia." (PMID 34679770, 2021). "High dietary Se may stimulate overexpression of glutathione peroxidase-1 (GPx-1) and other antioxidant selenoproteins, promoting insulin resistance and obesity or may induce the release of glucagon resulting in hyperglycemia." (PMID 32076615, 2020). "For example, overexpression of GPX1 was reported to exhibit insulin resistance and obesity in mice." (PMID 30425271, 2018). "Specifically, the action of intracellular ROS required for insulin sensitizing may be impaired by increased GPx1 activity resulting in progression of insulin resistance." (PMID 29662007, 2018). "GPx1 is considered to play important role in obesity, insulin resistance, and atherosclerosis." (PMID 29662007, 2018). "They stated that high-Se diets may stimulate the release of glucagon, promoting hyperglycemia, or induce overexpression of glutathione peroxidase-1 and other antioxidant selenoproteins resulting in insulin resistance and obesity." (PMID 24555483, 2014). "However, GPX1 knockout mice are protected against high-fat diet-induced insulin resistance and atherosclerosis." (PMID 24562334, 2014). "Conversely, overexpression of GPx1 promotes obesity and insulin resistance in mice, and supplementation with antioxidants may promote insulin resistance in humans." (PMID 23918226, 2013). "Induction of GPx-1 may also be a mechanism through which selenium exerts its potential diabetogenic effect, since transgenic animal models overexpressing GPx-1 have been reported to experience hyperinsulinemia and insulin resistance." (PMID 22073154, 2011). "Development of insulin resistance has been described in mice over-expressing GPx1." (PMID 20298544, 2010). "As GPx1 KO mice fed an obesogenic diet show decreased adiposity with unaltered insulin sensitivity and GPx1 overexpression causes obesity and insulin resistance, GPx1 function in adipose tissue might not explain the differences between studies." (PMID 35624726, 2022). "Additionally, diets rich in Se may increase the expression of glutathione peroxidase-1 and other anti-oxidant selenoproteins leading to insulin resistance and obesity." (PMID 32774440, 2020). "While this suggests increased ROS does not necessarily lead to hepatic insulin resistance and fatty liver disease, global GPx1 deletion and the general failure of these mice to gain fat mass makes it difficult to isolate direct effects of GPx1 loss on liver metabolism." (PMID 24672550, 2014). "Interestingly, mice that lack GPX1 are protected from a high fat diet-induced insulin resistance." (PMID 23603996, 2013).
Insulin resistance (continued). "Moreover, high-selenium diets may stimulate the release of glucagon, promoting hyperglycemia, or may induce over-expression of glutathione peroxidase-1 (GPx-1) and other antioxidant selenoproteins resulting in insulin resistance and obesity." (PMID 20858268, 2010). "The development of insulin resistance in mammals with elevated expression of an antioxidant enzyme and suggest that increased GPx-1 activity may interfere with insulin function by overquenching intracellular reactive oxygen species required for insulin sensitizing." (PMID 17825092, 2007). "Furthermore, glutathione peroxidase 1 (GPX1), a selenium-containing antioxidant enzyme, has been discovered to inhibit insulin signaling by lowering reactive oxygen species levels, resulting in insulin resistance and possibly affecting pancreatic β-cell function." (PMID 39149550, 2024). "Glutathione peroxidase 1 (GPX1) is an antioxidant enzyme involved in DCM development; it reduces the production of reactive oxygen species (ROS) in cardiomyocytes and improves insulin resistance." (PMID 38581056, 2024). "Mice lacking one of the key enzymes involved in the elimination of physiological ROS, glutathione peroxidase 1 (Gpx1), are protected against HFD-induced insulin resistance." (PMID 33795530, 2021). "Correspondingly, Gpx1−/− mice fed a HFD were characterized by significantly lower rate of hepatic steatosis and insulin resistance." (PMID 32344656, 2020). "Research has shown that excessive levels of GPX1 in mouse models can lead to insulin resistance and hyperinsulinemia, primarily due to the inhibition of normal insulin‐mediated Akt signaling." (PMID 40599237, 2025). "On the contrary, mice lacking Gpx1 were protected from insulin resistance induced by a high-fat diet, while administration of N-acetylcysteine (NAC), the Gpx1 substrate, rendered them insulin-resistant and increased fasting glucose levels." (PMID 33810179, 2021). "Mice lacking GPX1 were found protected from high-fat diet-induced insulin resistance and have a reduced fasting blood glucose and improved glucose tolerance." (PMID 29675131, 2018). "On the contrary, mice lacking Gpx1 were protected from high-fat diet-induced insulin resistance, while administration of NAC rendered them more insulin-resistant and increased fasting glucose levels in the blood." (PMID 23730255, 2012). "For instance, mice lacking glutathione peroxidase 1 (Gpx1), characterized by increased insulin sensitivity, were protected from high-fat-diet-induced insulin resistance." (PMID 23443131, 2012). "Our laboratory has applied knockouts of GPX1 (Gpx1-/-), SOD1 (Sod1-/-), and both (dKO) mice and GPX1-overexpressing (Gpx1-OE) mice to study the metabolic roles and molecular mechanisms of these redox enzymes in the development of insulin resistance and diabetes." (PMID 37107224, 2023). "Chronic ROS production by mitochondria may contribute to the development of insulin resistance, a primary feature of type 2 diabetes, but mice lacking glutathione peroxidase 1 were protected from high-fat-diet-induced insulin resistance." (PMID 21750704, 2011).